TFF3 (trefoil factor 3)
Diseases named in the same sentence as TFF3 in open-access papers (continued):
Sharing a sentence is not in itself a finding about the gene and the disease.
breast carcinoma (57 papers, 2003 to 2026). "COX6C is linked to drug resistance, while TFF3 serves as a marker of differentiation and progression in breast cancer, particularly in DCIS, where it reflects a differentiated and secretory phenotype." (PMID 41182757, 2025). "Trefoil factor 3 (TFF3) expression was found to be associated with residual breast carcinoma following neoadjuvant chemotherapy in 133 cases from the UAE, suggesting that its expression is associated with increased resistance to chemotherapy." (PMID 38001658, 2023). "TFF3 was observed to be associated with a subset of CTCs with epithelial-like features in the experimental model and in a cohort of 44 breast cancer patients, and to play a role in cell migration, invasion and blood-borne dissemination." (PMID 35216615, 2022). "TFF3 is also associated with breast cancer metastasis, where its expression predicts poor survival, and it is also associated with residual invasive disease following neoadjuvant chemotherapy in breast carcinoma." (PMID 35992833, 2022). "The expression of TFF3 is significantly associated with residual breast carcinoma following neoadjuvant chemotherapy suggesting its expression is associated with increased resistance to chemotherapy." (PMID 30744593, 2019). "Ectopic TFF3 expression in cancer tissues like gastric, pancreatic, hepatocellular, colon, and breast cancer is linked to enhanced cell proliferation and survival as well as increased invasion and migration." (PMID 31450568, 2019). "On the same track we also have shown a significant co-localization of TFF3 and p- AKT-1 in breast carcinoma cells in residual tumors suggesting a possible association between TFF3 and AKT-1 in incomplete pathological response group." (PMID 30744593, 2019). "Trefoil factor 3 (TFF3) expression is positively associated with advanced clinicopathological features of mammary carcinoma (MC)." (PMID 30451834, 2018). "In HER2+/ER+ breast cancer cells with acquired trastuzumab resistance, TFF3 expression was markedly upregulated and associated with a corresponding decrease in HER signalling." (PMID 29088778, 2017). "TFF3 promotes breast cancer progression and has been implicated in anti-estrogen resistance in breast cancer." (PMID 29088778, 2017). "Other genes present in our MINT gene signature include XPB1, AGR3, CCDC170 and TFF3 that were reported as being associated with breast cancer." (PMID 28241739, 2017). "In contrast, TFF3 protein overexpression has been linked with aggressive disease in colon, gastric, and mammary cancer." (PMID 28930171, 2017). "The present study aims were to validate microarray studies that demonstrate TFF3 regulation by oestrogen and its association with oestrogen receptors in breast cancer, to evaluate TFF3 as a biomarker of endocrine response, and to investigate TFF3 function." (PMID 25900183, 2015). "Trefoil factor-3 (TFF3) is an oncogene secreted from mammary carcinoma cells and associated with poor prognosis." (PMID 26559818, 2015). "TFF3 is an estrogen regulated gene in mammary carcinoma and its TFF3 expression is generally positively associated with mammary carcinoma of the estrogen receptor positive (ER+) subtype." (PMID 26559818, 2015). "Further, TFF3 expression is associated with poor survival outcome in patients with ER+ mammary carcinoma." (PMID 26559818, 2015). "TFF3 expression is elevated and often associated with prognosis in gastric, colorectal, hepatocellular, thyroid, lung, pancreatic, prostate, cervical, endometrial, and ER+ mammary carcinomas." (PMID 39920140, 2025). "In addition, increased expression of TFF3 is associated with poor prognosis of patients with various cancers, such as colorectal, gastric, hepatocellular, and mammary carcinomas." (PMID 35332126, 2022).
breast carcinoma (continued). "Lastly, we would suggest that cellular localization of TFF3 protein should be analyzed together with expression levels, as localization has been suggested to impact the association between TFF3 protein and cancer aggressiveness in breast cancer." (PMID 28930171, 2017). "Furthermore, several studies have also implicated functional involvement of TFF3 in resistance towards tamoxifen and aromatase inhibitors in mammary carcinomas." (PMID 28445151, 2017). "Notably, it can be determined if there exists a clinical correlation between the loss of HER2 and increased TFF3 expression in trastuzumab resistant HER2+/ER+ breast cancer." (PMID 29088778, 2017). "Thus, in breast cancer, high TFF3 protein expression has been associated with low grade disease in early stages, but with aggressive disease in advanced stages." (PMID 28930171, 2017). "Furthermore, TFF3 expression is associated with increased microvessel density, both in gastric and mammary carcinoma." (PMID 26559818, 2015). "Further underlining that TFF3 can function as an oncogene or a tumor suppressor depending on the cell type, previously reported functional studies have shown that TFF3 overexpression promoted proliferation in a breast cancer cell line, but inhibited proliferation in a thyroid cancer cell line." (PMID 28930171, 2017). "For example, TFF3 is in the set of genes that decreases in expression in M vs. E type breast cancer cell lines." (PMID 41223092, 2025). "Emerging evidence suggests that TFF3 is significantly upregulated in cancers such as gastric cancer, colorectal cancer, lung cancer, thyroid cancer, and breast cancer and that it plays a key role in tumor progression." (PMID 35039476, 2022). "Studies showed that AMPC dose-dependently decreased TFF3 expression in estrogen-receptor-positive mammary carcinoma cells, lung adenocarcinoma cells, and mesenchymal colorectal carcinoma cells, which induced tumor-volume reduction in mice." (PMID 35039476, 2022). "We have also explored the function of TFF3, one of the genes up-regulated in CTCs compared to the primary tumor, which is known to characterize the luminal breast cancer subtype." (PMID 35216615, 2022). "Within this group of selected genes, we found the family of trefoil factor secreted peptides TFF1, TFF2 and TFF3, which are known to characterize luminal breast cancers." (PMID 35216615, 2022). "TFF1 and TFF3 overlapped frequently among the top 200 genes for breast cancer cell lines and 8 cancer drugs used in our study." (PMID 34693378, 2021). "We have shown a significant correlation between the expression of TFF3 in breast carcinoma cells and response to neoadjuvant chemotherapy." (PMID 30744593, 2019). "The study was designed to determine the role of TFF3 in breast cancer chemoresistance with the aim of establishing TFF3 expression as a biomarker for drug resistance." (PMID 30744593, 2019). "There was a significant correlation between the expression of TFF3 in breast carcinoma cells and response to neoadjuvant chemotherapy (p = 0.0165)." (PMID 30744593, 2019). "There was significant co-expression of TFF3 and NF Kappa-B in breast carcinoma cases treated with neoadjuvant therapy (p = 0.0243)." (PMID 30744593, 2019). "The increased expression of TFF3 in breast carcinoma will promote their survival and make them resistance to neoadjuvant therapy." (PMID 30744593, 2019). "TFF3 has also been reported to mediate both tamoxifen and trastuzumab resistance in human mammary carcinoma, as well as doxorubicin resistance in hepatocellular carcinoma." (PMID 31658702, 2019). "Furthermore, TFF3 has been implicated in reduced sensitivity and acquired resistance to chemo-, hormonal, and targeted therapies in different cancers; and in particular, mammary carcinoma with acquired trastuzumab resistance exhibited a shift in oncogene addiction from HER2 to TFF38,10,21." (PMID 31685806, 2019).
breast carcinoma (continued). "We also have identified a significant co-localization between TFF3 and NF Kappa B in breast carcinoma cells in residual tumor suggesting a possible role in the development of incomplete pathological response." (PMID 30744593, 2019). "There was significant co-expression of TFF3 with AKT1 (p = 0.0365), BCl2 (p = 0.0152), and NF Kappa-B (p = 0.0243) in breast carcinoma cases with residual carcinoma following neoadjuvant therapy which support the role of TFF3 in chemoresistance." (PMID 30744593, 2019). "We have also shown co-localization of TFF3 with anti-apoptotic protein in residual breast carcinoma." (PMID 30744593, 2019). "There was significant co-expression of TFF3 and BCl2 in breast carcinoma cases treated with neoadjuvant therapy (p = 0.0152) suggesting anti-apoptotic role of TFF3." (PMID 30744593, 2019). "The higher levels of TFF1 and TFF3 mRNA in CTCs of some metastatic breast cancer patients confirmed that they act as tumor progression factors." (PMID 29977293, 2018). "As regards the level of TFF3 mRNA in CTCs in ER + breast cancer tissue, we found 68.8% (11 of 16) of patients with high TFF3 level had ER + primary tumor." (PMID 29977293, 2018). "They explained this by the increase in hypoxanthine-guanine phosphoribosyl transferase (hHPRT) activity in lung of mice with ER+ mammary carcinoma cell lines that developed increased expressed TFF3." (PMID 29977293, 2018). "The regulation of TFF3 expression upon HER2 inhibition by trastuzumab in HER2+/ER+ breast cancer cells was also investigated under both estrogen-depleted and -replete conditions." (PMID 29088778, 2017). "The origin of high serum TFF3 in breast cancer patients also has possibility of different organ from breast cancer." (PMID 28687783, 2017). "Serum TFF1 and TFF3 levels in breast cancer patients were significantly higher than in the healthy individuals." (PMID 28687783, 2017). "Serum screening with TFF1, TFF2, and TFF3 for breast cancer can increase the screening receiving rate." (PMID 28687783, 2017). "Taken together, it is proposed that HER2 regulates its own signalling in a negative feedback loop through transcriptional repression of TFF3 in HER2+/ER+ breast cancer cells." (PMID 29088778, 2017). "Immunohistochemical staining for TFF1 was positive in 56.5% of breast cancer tissues and TFF3 was positive in 73.9% of breast cancer tissues." (PMID 28687783, 2017). "Serum TFF1, TFF2, and TFF3 in 94 breast cancer patients and 84 healthy individuals were measured and compared." (PMID 28687783, 2017). "Herein, we observed that the trastuzumab resistant HER2+/ER+ breast cancer cells displayed a shift in oncogene addiction away from HER2 to TFF3 with highly upregulated TFF3 expression and downregulated HER signalling." (PMID 29088778, 2017). "TFF3, behaved as an oncogene, promotes cancer cell proliferation, survival, oncogenicity and invasion in various cancers, such as mammary carcinoma, gastric cancer and prostate carcinoma." (PMID 28070169, 2017). "In this study, we showed that the cross-regulation between HER2 and TFF3 identifies TFF3 as a mediator of trastuzumab resistance in HER2+/ER+ breast cancer." (PMID 29088778, 2017). "Immunohistochemical staining (IHC) for TFF1, TFF2, and TFF3 was performed for breast cancer tissue and normal epithelial tissue surrounding breast cancer." (PMID 28687783, 2017). "In order to confirm the functional roles of TFF3 in acquired trastuzumab resistance in HER2+/ER+ breast cancer cells, we depleted endogenous TFF3 in trastuzumab resistant BT474 cells with siRNA against TFF3." (PMID 29088778, 2017). "In contrast, TFF3 has been observed to be prominently elevated in cervical, endometrial and mammary carcinoma." (PMID 29100386, 2017). "Firstly, the mechanisms of HER2 transcriptional regulation of TFF3 in different breast cancer subtypes are probably varied." (PMID 29088778, 2017).
breast carcinoma (continued). "For evaluation of the serum TFF1, TFF2, and TFF3 for cancer screening, serum of 22 breast cancer patients before treatment were evaluated." (PMID 28687783, 2017). "The effect of AMPC inhibition of TFF3 on acquired trastuzumab resistance in HER2+/ER+ breast cancer cells was also investigated." (PMID 29088778, 2017). "Our previous study has suggested that TFF3 promotion of oncogenic behavior in breast cancer cells is BCL-2 dependent." (PMID 28445151, 2017). "We have previously shown that TFF3 activates cell survival signaling pathways which contribute to anti-estrogen resistance in mammary carcinoma." (PMID 28445151, 2017). "Serum TFF l and TFF3 levels in breast cancer patients were significantly higher than in healthy individuals." (PMID 28687783, 2017). "Consistently, TFF3 has previously been shown to promote migration and invasion of breast cancer cells, and modulate the expression of epithelial, mesenchymal and metastatic gene markers." (PMID 28445151, 2017). "Herein, we have provided further evidence of the role of TFF3 in promoting CSC-like behaviour in trastuzumab resistant HER2+/ER+ breast cancer." (PMID 29088778, 2017). "In our cohort, TFF1 was positive in normal epithelial tissue surrounding breast cancer in 8.7% of patients and TFF3 was positive in normal epithelial tissue surrounding breast cancer in 21.7% of patients." (PMID 28687783, 2017). "TFF1, TFF2, and TFF3 values were all statistically different between breast cancer patients and healthy individuals." (PMID 28687783, 2017). "Collectively, our results suggest that TFF3 functionally mediates trastuzumab resistance in HER2+/ER+ breast cancer cells." (PMID 29088778, 2017). "Given the bidirectional crosstalk between HER2 and ERα, the transcriptional regulation of estrogen-responsive TFF3 by HER2 in HER2+/ER+ breast cancer cells was investigated." (PMID 29088778, 2017). "Serum TFF1 and TFF3 levels in breast cancer patients were significantly higher than in healthy individuals." (PMID 28687783, 2017). "TFF3 participated in cancer invasion metastasis in breast cancer through repression of CDH1 mediated by STAT3." (PMID 28070169, 2017). "We further examined the effect of siRNA-mediated TFF3 depletion or TFF3 inhibition on trastuzumab response in HER2+/ER+ breast cancer cells using 3D Matrigel growth assays." (PMID 29088778, 2017). "TFF3, behaved as an oncogene, promotes proliferation and invasion, improves survival, and increases oncogenicity in cancer cells, such as mammary carcinoma, gastric cancer and prostate carcinoma." (PMID 28070169, 2017). "Along this line, TFF3 overexpression is frequently observed in gastric, pancreatic, hepatocellular, colon and breast cancer." (PMID 27626280, 2016). "In contrast to our results, transfection of colon cancer cells with TFF3 enhanced their ability to block apoptosis and in MCF-7 human mammary carcinoma cells forced expression of TFF3 reduced apoptosis." (PMID 27626280, 2016). "By contrast, forced expression of TFF3 in prostate cancer and mammary carcinoma cells enhances anchorage-independent growth and 3-D colony formation." (PMID 27626280, 2016). "It has been shown that forced expression of TFF3 in mammary carcinoma cells increased tumor size, contradicting our findings that TFF3 overexpression reduced the size of tumors forming from RB cells grafted on the CAM." (PMID 27626280, 2016). "Forced TFF3 expression in mammary carcinoma and prostate cancer cells likewise promoted cell migration and invasion." (PMID 27626280, 2016). "Herein, we report that TFF3 secreted from mammary carcinoma cells promotes de novo angiogenesis, both directly by TFF3 stimulation of endothelial cells and indirectly via enhanced IL-8 expression, which subsequently regulates endothelial cell function." (PMID 26559818, 2015).
breast carcinoma (continued). "Consistent with our previous study, which showed that TFF3 is associated with lymphatic, vascular, neural and muscle invasion in breast cancer, TFF3 promoted cell migration and invasion." (PMID 25900183, 2015). "TFF3 exerted its angiogenic effects on endothelial cells directly as well as indirectly via enhancement of the expression of IL-8 from both mammary carcinoma and endothelial cells." (PMID 26559818, 2015). "Functionally, TFF3 has recently been demonstrated to stimulate cellular invasion and metastasis of ER+ mammary carcinoma cells in a Src-STAT3 dependent manner." (PMID 26559818, 2015). "TFF3 was induced by oestrogen, and its induction was inhibited by antioestrogens, tamoxifen, 4-hydroxytamoxifen and fulvestrant in oestrogen-responsive breast cancer cells." (PMID 25900183, 2015). "The aims of the present study were to validate the microarray analyses, to determine the value of TFF3 as an independent predictive biomarker of response to endocrine therapy and to evaluate the response of breast cancer cells to TFF3." (PMID 25900183, 2015). "TFF3 has previously been demonstrated to stimulate survival, invasion, and metastatic expansion of mammary carcinoma." (PMID 26559818, 2015). "Herein, we demonstrate that TFF3 produced in mammary carcinoma cells functions as a promoter of tumor angiogenesis." (PMID 26559818, 2015). "Forced expression of TFF3 in mammary carcinoma cells stimulated IL-8 transcription and subsequently enhanced IL-8 expression in both mammary carcinoma cells and HUVEC." (PMID 26559818, 2015). "Our demonstration that TFF3 protein is regulated by oestrogen and inhibited by antioestrogens in oestrogen-responsive breast cancer cells supports the potential of TFF3 protein as a biomarker of oestrogen dependence." (PMID 25900183, 2015). "Mammary carcinoma cells with forced expression of TFF3 were transiently transfected with an IL-8 promoter reporter (full length, -4800 to +104 bp) and a pRL-CMV control reporter vector." (PMID 26559818, 2015). "We next examined the effects of depletion of endogenous TFF3 in mammary carcinoma cells on the angiogenic behavior of HUVEC by use of siRNA." (PMID 26559818, 2015). "That TFF3 stimulates migration and the invasion of breast cancer cells suggests that removal of these effects during anti-endocrine therapy would be beneficial to patients in whose tumour cells TFF3 is expressed under the control of oestrogens." (PMID 25900183, 2015). "Recent expression microarray analysis identified TFF3 as one of relatively few genes whose expression is regulated consistently by oestrogen in oestrogen-responsive breast cancer cell lines." (PMID 25900183, 2015). "We demonstrated that TFF3 secreted by mammary carcinoma cells promoted proliferation and survival of HUVEC." (PMID 26559818, 2015). "Depletion of IL-8 in mammary carcinoma cells with forced expression of TFF3, or antibody inhibition of IL-8, partially abrogated mammary carcinoma cell TFF3-stimulated HUVEC angiogenic behavior in vitro, as did inhibition of the IL-8 receptor, CXCR2." (PMID 26559818, 2015). "We have proposed a schematic model of the mechanism by which TFF3 in promotes angiogenesis in mammary carcinoma." (PMID 26559818, 2015). "We therefore conclude that TFF3 secreted from mammary carcinoma cells stimulated angiogenic behavior of HUVEC through IL-8/CXCR2 signaling." (PMID 26559818, 2015). "Forced expression of TFF3 in mammary carcinoma cells has previously been demonstrated to promote proliferation, survival and invasion." (PMID 26559818, 2015). "The data indicated that TFF3 merited investigation as an oestrogen-responsive biomarker in breast cancer patients." (PMID 25900183, 2015). "TFF3 stimulated also the invasion of breast cancer cells through collagen IV in a modified Boyden chamber assay." (PMID 25900183, 2015). "We further determined if TFF3 secreted from mammary carcinoma cells modulates the angiogenic behavior of HUVEC." (PMID 26559818, 2015).